IL6 (interleukin 6)
Diseases named in the same sentence as IL6 in open-access papers (continued):
Sharing a sentence is not in itself a finding about the gene and the disease.
infection (continued). "Inhibition of the classic IL-6 signaling pathway is thought to be a factor in both increased risk of infection and gastrointestinal AEs due to hampered intestinal wound healing." (PMID 39857830, 2025). "In the PKR-deficient control cells, MYXV∆029L∆156R infection led to a strong induction of TNFα and IL-6 expression." (PMID 40872887, 2025). "Comorbidities, history of infection and kidney disease were associated with choosing anti-IL-6 bDMARDs in biologic-naïve RA patients in Wales." (PMID 39698233, 2025). "Elevated IL-6 levels have been associated with early and late-onset NS, showing potential as an early indicator of infection before the onset of clinical symptoms." (PMID 40242671, 2025). "Prompt initiation of anti-TB drugs, including isoniazid, rifampicin, pyrazinamide, and ethambutol, targets the underlying infection and subsequently reduces systemic inflammation by decreasing the release of pro-inflammatory cytokines such as IL-6." (PMID 39941433, 2025). "These patients typically have CD8+ T cell deficiency and increased IL-6 concentrations, which is thought to weaken their immune response and increase their vulnerability to severe infections." (PMID 40489562, 2025). "In a multivariate model adjusted for age, injury severity, and hospital infections, day-0 IL-6 was independently associated with 6-month adverse outcomes (OR 1.15, 95% CI 1.1–1.2, P = 0.031)." (PMID 40713822, 2025). "previously introduced a diagnostic approach combining the “double peaks of IL-6” pattern with a three-cytokine-based prediction model to rapidly identify severe infections following CAR-T cell infusion." (PMID 41347097, 2025). "When adjusted for age, severity of injury,and the presence of a hospital infection, day-0 IL-6 was significantly associated with the adverse outcome at 6 months (OR 1.15 95% CI 1.1–1.2, p = 0.031)." (PMID 40713822, 2025). "Elevated IL-6 levels reflect the acute phase response essential for infection control but also associated with severe complications if dysregulated." (PMID 40061813, 2025). "The increases in IL-6 and IL-1β levels at 5 dpi are consistent with the high mortality rate associated with infection by the HY/HA-ΔL226/R229I strain." (PMID 40338080, 2025). "Both IL-1β and IL-6 are synergistic acute-phase cytokines that initiate systemic responses to infection and are associated with chronic inflammatory diseases." (PMID 41041334, 2025). "In contrast to our expectation, we found that infection of T24/83 cells with the tcpC-deficient CFT073ΔtcpC strain resulted in statistically significant lower amounts of IL-6 and TNFα." (PMID 41310197, 2025). "It was also shown that the risk of infection development was higher among individuals receiving IL-6 and IL-1 inhibitors." (PMID 40573975, 2025). "In contrast, Cy-treated animals exhibited elevated IL-6 levels associated with the resolution of infection, suggesting an anti-inflammatory role of IL-6 and reiterating the ambiguity of this cytokine." (PMID 40920877, 2025). "Maximum IL-6 concentrations were associated with postoperative infection (adjusted odds ratio (aOR) 1.04 per 10 pg/ml, 95% confidence interval (CI) 1.00–1.09, p = 0.047) as was CRP (aOR 1.01 per mg/L, 1.00–1.03, p = 0.032)." (PMID 40549692, 2025). "A linear regression analysis was performed to evaluate the association between HAdV-36 infection and levels of IL-10, IL-2, IL-6, IL-8, and TNF-α." (PMID 40284995, 2025). "Together, this lack of lymphocytes and elevated concentrations of inflammatory cytokines (i.e., IL-6) results in a weakened immune response against acute infections including ones caused by respiratory viruses, resulting in severe infections." (PMID 40489562, 2025). "While the Th1 response is associated with host resistance to the parasite, the Th2 response through the expression of IL-4, IL-6, and IL-10 is associated with greater susceptibility to infection." (PMID 40572185, 2025).
infection (continued). "IL‐6, a key cytokine in infection‐associated inflammation, has been implicated in ovarian immune regulation and tissue homeostasis." (PMID 41268882, 2025). "Pro-inflammatory cytokines, such as TNF-α, IL-6, and IL-8, are released during inflammation caused by infection." (PMID 40278397, 2025). "As with biologic medication, the risk of infections in RA patients treated with IL-6 inhibitors has also been reported." (PMID 39698233, 2025). "Accordingly we believed that the decrease in IL-6 was caused by a decrease in the level of infection." (PMID 39792837, 2025). "In infection, numerous studies (including by ourselves) have shown differential effects on the risk of infection with IL-6 inhibition." (PMID 40435229, 2025). "IL-6 contributes to the regulation of physiological immune defense mechanisms against infection but is also implicated in maladaptive processes driving pathological hyperinflammation." (PMID 41155261, 2025). "The high inflammatory load and increased levels of circulating IL-6 as a result of cytokine storm during COIVD-19 infection can underly the precipitation of cardiovascular events." (PMID 40026602, 2025). "This adds a level of complexity; therefore, biomarkers more associated with infection than inflammation had a discriminative advantage over the inflammatory markers, e.g., IL-6, IL-8, CRP, PCT, lactate, TREM-1, and uPAR." (PMID 39857101, 2025). "Adiposopathy is associated with elevated production of proinflammatory cytokines, such as TNF-α and IL-6, which can impair wound healing, increase the risk of infection, and worsen post-operative outcomes." (PMID 40563674, 2025). "When the body detects an infection or inflammation, it releases certain chemicals (like IL-1 and IL-6) that cause fever." (PMID 39888966, 2025). "IL-6 levels were also influenced by sex and age, whereas ferritin levels were associated with the site of infection." (PMID 41472286, 2025). "Activates macrophages; IFNγR1 deficiency increases infection risk in mice; enhances IL-6, TNF-α production." (PMID 41268545, 2025). "A study conducted by Lepiller and colleagues demonstrated that the infection of HepG2 cells with human cytomegalovirus (HCMV) caused the production of IL-6 in the supernatants of HepG2 cells, starting as early as 2 h post-infection." (PMID 40843809, 2025). "Basically, CRP is synthesized by IL-6 in the liver, and these molecules are produced in large quantities when the body becomes susceptible to infection; because of this reason, they are easily found in serum." (PMID 40095921, 2025). "The current experimental study using C57BL/6 female hACE2 mice infected with SARS-CoV-2 Omicron variant provides evidence on IL-6 and CD11d overexpression in cardiac tissue, 28 days after the infection (post-COVID condition)." (PMID 41472298, 2025). "It has been reported that astrocyte-derived IL-6 is associated with neuropathological changes upon EV-A71 infection." (PMID 39679722, 2025). "Inflammation, oxidative stress, and pruritus exacerbate dryness, infection risk, and delayed healing, while IL‐6 and TNF‐α hinder moisture retention and protection." (PMID 40405557, 2025). "Correlation analyses revealed significant inverse associations between serum levels of VA and VD and the infection marker procalcitonin (PCT) as well as the inflammatory marker interleukin-6 (IL-6)." (PMID 41311806, 2025). "IL-6 was associated with postoperative infection, independent from the core model predictors (aOR 1.04 per 10 pg/ml, (95% CI 1.00,1.09)), and improved model fit when added to the core model (LRT p = 0.048)." (PMID 40549692, 2025). "IL-6 is a pro-inflammatory cytokine and plays a central role in the acute-phase response to infection and is associated with both systemic inflammation and infection-related complications." (PMID 40806991, 2025). "IL-6, IL-8, and IP-10 were induced after infection and have been associated with worse outcomes in COVID infection." (PMID 41157615, 2025).
infection (continued). "Scientists have therefore developed more targeted (selective) IL-6 inhibitors that are less likely to increase the risk of infections." (PMID 39857830, 2025). "Others have shown that iron supplementation alone increases pro-inflammatory cytokines, in particular IL-6, and decreases ferroportin production and contributes to iron overload and an increased risk of infection." (PMID 38892681, 2024). "The secretion of interleukin 6 (IL-6), a pro-inflammatory cytokine, is triggered by infection, causing this release." (PMID 39453270, 2024). "Our research shows that infection of rabbits with L. europaeus/GI.1, and GI.2 genotypes causes an overexpression of two critical acute phase cytokines—IL-6 in all examined tissues and TNF-α (in the liver, lungs, and spleen)." (PMID 39273479, 2024). "While IL-10 is known to dampen inflammation, the IL-6 is a pleotropic cytokine whose biological functions have also been linked to immunomodulation during the stages of infection resolution." (PMID 38683795, 2024). "Elevated IL-6 levels post-procedure can signify tissue damage and inflammation, potentially indicating infection risk, especially after URS." (PMID 38327930, 2024). "A higher EPA/AA ratio prior to infection was found to be associated with lower concentration of C-Reactive Protein and interleukin-6, leading to a better prognosis of hospitalized SARS-CoV-2 patients." (PMID 38702342, 2024). "The presence of these cytokines indicates pro-inflammatory processes, with IL-6 being associated with the response to infection and tissue damage and IL-4 with the production of immunoglobulin E, regulation of cell proliferation and apoptosis." (PMID 39015324, 2024). "Studies have shown that Cryptosporidium can cause the increase of TNF-α and IL-6 after infection of dairy cows, causing inflammation." (PMID 38914662, 2024). "The transfusion of ANH was found to trigger complement system activation and elevated plasma levels of IL-6 in healthy volunteers over a 7-day period in a previous study, potentially contributing to a decrease in the postoperative infection risk." (PMID 38789959, 2024). "CETPi treatment was also associated with decreased IL-6 levels in bronchoalveolar lavage fluid (BAL) at 72 hours after infection." (PMID 38646937, 2024). "Among the subclasses, IgG 1, IgG 2 ang IgG 4 levels were negatively associated with IL-6 concentration, and were positively associated with IL-10 concentration in maternal peripheral plasma at the first infection." (PMID 39495782, 2024). "Elevated levels of Infection-associated tests include SAA, PCT, CRP, and IL-6 indicate the presence of infection." (PMID 39267743, 2024). "IL-6 expression was upregulated by infection and tended to be lower in CCR2-deficient mice than in WT mice, although the difference was not statistically significant." (PMID 39051675, 2024). "Subgroup analysis reveals that patients with elevated IL-6 levels during infection face a greater risk of 28-day all-cause mortality, irrespective of the levels of other commonly used inflammation indicators or clinical scores." (PMID 39212218, 2024). "Another challenge that must be addressed is the potential immunosuppressive effect of IL-6-targeted therapy and attendant increased risk of infection." (PMID 38689325, 2024). "Infection with either virus induced the secretion of IL-6, and IL-6 levels were reduced when CAD-deficient cells were infected." (PMID 38849575, 2024). "As the infection progressed, mice deficient in IL-6 had similar histological respiratory disease development compared to animals with intact IL-6 responses or supplemented with the exogenous cytokine." (PMID 39334365, 2024). "During infection, an elevation in hepcidin level caused primarily by the stimulatory effect of interleukin 6 (IL-6) leads to the development of hypoferremia." (PMID 38892911, 2024).
infection (continued). "IL-6 is a cytokine with multiple functions that mediate the response to infection or injury and participates in tumourigenesis caused by activation of JAK2/STAT3 signaling." (PMID 39103836, 2024). "Our results provide clear evidence that TPF downregulates key antiviral and pro-inflammatory genes, including IFN-β, MX2, and IL6, thereby enhancing the susceptibility of cancer cells to VSVΔ51 infection." (PMID 38932212, 2024). "A meta-analysis showed that serum IL-6 has moderate diagnostic value and potential clinical value in differentiating infection in critically ill patients." (PMID 38504206, 2024). "Amygdalin also has anti-inflammatory effect, which can significantly reduce the increase of IL-1β and IL-6 inflammatory factors caused by infection." (PMID 39283878, 2024). "Spearman analysis showed a trend (P = 0.06) to associate secondary infection with IL-6 (r = 0.76) and BUN (r = 0.76)." (PMID 36747045, 2023). "IL-6 is a cytokine with the fastest response to injury and infection and has high diagnostic value in the early stage of infection." (PMID 36691058, 2023). "Pro-inflammatory cytokines, such as IL-1β and IL-6, can mediate host inflammatory processes and produce a rapid immune response after infection with pathogenic microorganisms." (PMID 37835612, 2023). "At the same time, a large of pro-inflammatory cytokines (interleukin-6, C-reactive protein, tumor necrosis factor-α, etc.)are synthesized and secreted upon pathogenic infection." (PMID 38223568, 2023). "In chronic stress, early trauma, and acute inflammation caused by infection, the expression of IL-6, a proinflammatory biomarker, is increased along with various putative biomarkers of inflammation, including TNF-α and CRP106." (PMID 36599852, 2023). "It is recommended that cattle exhibiting serum IL-6 concentrations above 85.16 pg/mL should be given attention, as they are susceptible to developing a prolonged infection duration." (PMID 36679958, 2023). "Studies have shown that IL-6 inhibition leads to an increased risk of TB; it is often considered one of the essential cytokines during infection." (PMID 37243059, 2023). "Studies have been documented suggesting that the synergistic interaction between IL-6 and interleukin 17 (IL-17) have been associated with viral persistence and exacerbated clinical outcome during infection with Theiler's murine encephalomyelitis virus (TMEV)." (PMID 36707891, 2023). "The inflammatory conditions and host responses to infection cause the release of interleukin-6 and other cytokines that trigger the synthesis of CRP and fibrinogen by the liver." (PMID 37461754, 2023). "Upon infection, S. aureus induces the expression of genes encoding pro-inflammatory cytokines, including IL-6, IL-1β, and TNF-α." (PMID 37759998, 2023). "A reduced level of IL-6 and reduced number, and cytotoxicity, of NK cells under DR were associated with reduced survival of mice upon infection." (PMID 36399256, 2023). "Higher levels of inflammatory cytokines such as IL‐6 in bronchoalveolar lavage fluids (BALFs) have been associated with severe COVID‐19 infection compared to moderate infection." (PMID 38099246, 2023). "Interleukin-6 (IL-6) is a proinflammatory cytokine that plays a crucial role in various immunological processes associated with host infection, inflammatory disorders, hematopoiesis, and oncogenesis." (PMID 37762312, 2023). "Several studies have shown that impaired IL-6 function enhances susceptibility to infection with various pathogens." (PMID 38053527, 2023). "The almost double CRP and much higher IL-6 values indicate that the pro-inflammatory picture is much more pronounced during the infection with this variant." (PMID 37834972, 2023). "High levels of IL-6 in body fluids are associated with acute localized bacterial infections and are an anti-inflammatory factor and mediator of the infection response." (PMID 37402969, 2023).
infection (continued). "We found that ‘LCN2(NGAL),’ ‘MHCII expression by monocytes,’ ‘IL-6,’ and ‘Anticoagulant treatment’ revealed distinct patterns associated with severe infection outcomes." (PMID 37598150, 2023). "Activated alveolar macrophages and lymphocytes secrete IL‐6, IL‐10, and chemokines, causing neutrophils to migrate to infection sites." (PMID 37249293, 2023). "In the majority of studies, IL-6 was also associated with infection compared to controls, and was the only biomarker to consistently demonstrate higher levels in UTI compared to ASB, including in older adults." (PMID 36761839, 2023). "Dysregulation of pro-inflammatory cytokines (TNF-α, IL-1β and IL-6) and anti-inflammatory cytokines (IL-10) are often associated with life-threatening infection or presence of endotoxin." (PMID 37424774, 2023). "Pro-inflammatory cytokines, such as IL-1α, TNF-α, and IL-6 have also been linked to lymphoid hyperplasia in the initial stages of the infection." (PMID 36766408, 2023). "Highlevels of IL-6 are associated with greater severity in patients with CD and inmurine infection models." (PMID 37878830, 2023). "It is well acquired that IL-6, a prototype cytokine with pleiotropic activity, is one of the primary agents involved in the inflammatory response to infection caused by viruses, including SARS-CoV-2." (PMID 37896877, 2023). "Beyond its crucial role in immunology, infection, and inflammation, IL6 is also a homeostatic regulator implicated in energy, glucose, protein, and lipid metabolism." (PMID 36986146, 2023). "This decrease in IL-6 led to an increased susceptibility to TB in terms of the post-infection life span." (PMID 37243059, 2023). "Serum samples were collected on the third day post-infection prior to mouse sacrifice, and IL-6 levels in serum were measured via an enzyme-linked immunosorbent assay." (PMID 38203508, 2023). "In the present study, compared with WT zebrafish, AST and ALT levels were lower in the livers of il-6−/−zebrafish after infection with A. hydrophila, suggesting that il-6 mutation in zebrafish attenuates A. hydrophila-induced liver injury." (PMID 38139043, 2023). "Infection with A. actinomycetemcomitans caused a significant upregulation in the expression levels of Isg15, Mx1, Mx2, Irf3, Irf7, Tlr-2, Tnf-α, Cxcl-1, and Il-6 genes." (PMID 37929187, 2023). "As IL-6 stands out as a major marker for inflammation induced by such virulent infections, its levels were measured via an enzyme-linked immunosorbent assay." (PMID 38203508, 2023). "For instance, IL-6 deficiency increased mortality in mice after infection with HSV and influenza virus." (PMID 38053527, 2023). "The proinflammatory cytokine IL-6 can strongly induce increased expression of IFITM3, and infection of IFITM3-deficient mice with cytomegalovirus resulted in higher levels of IL-6 production." (PMID 37602193, 2023). "The modulation of IL-6 dynamics and its multiple different signalling pathways represents a potentially exciting therapeutic opportunity for severe infection given the key role for this cytokine and associated signalling." (PMID 36716318, 2023). "Increased expressions of IL-6 in COVID-19 infection causes damage to lung tissue and development of infection." (PMID 37889917, 2023). "This emphasized that the involvement of IL-10 and IL-6 in the immune response of channel catfish plays a key role in assisting with organism protection against pathogenic infections as well as tissue repair." (PMID 37513733, 2023). "This unique inhibitory pathway involving intermediate IL-6 secretion expands our understanding of the overall weak responses of neonates to vaccines and their susceptibility to infections." (PMID 36735294, 2023). "The genes encoding for markers of inflammation, namely Tnf, Il1b, Il6, Il23a, and Cxcl10 were induced with infection in Tln1fl/fl mice and significantly decreased in the colon tissues from infected Tln1Δmye mice compared to infected Tln1fl/fl mice." (PMID 38102166, 2023).